IL6 (interleukin 6)
Diseases named in the same sentence as IL6 in open-access papers (continued):
Sharing a sentence is not in itself a finding about the gene and the disease.
infection (continued). "We next investigated whether IL-6 deficiency affects IFN-I activity in mice following WNV NY99 infection." (PMID 38053527, 2023). "In addition, IL-6-deficient mice showed reduced phagocytic activity of macrophages during infection." (PMID 37152296, 2023). "An increase in serum IL-6 levels is associated with trauma, infection, and surgery." (PMID 36299571, 2022). "Also, IL6 encodes a cytokine that functions in inflammation and the maturation of B cells, contributing to host defense during infection and tissue injury." (PMID 36209057, 2022). "Guided by our transcriptomic results indicating that a critical subset of inflammatory mediators are controlled by CASP11, we measured levels of CXCL1, IL-1β, and IL-6 by enzyme-linked immunosorbent assay (ELISA) in lung homogenates from infected animals at 2 and 4 d after infection." (PMID 35588457, 2022). "We believe this may be a timing issue as our current hypothesis is that infection causes systemic inflammation (i.e., increases in IL-6), followed by brain inflammation and subsequent neuronal dysfunction and behavioral impairment." (PMID 36380004, 2022). "Interestingly, the inflammatory cytokine interleukin-6 (IL-6) released in response to inflammation or infection causes the upregulation of hepcidin, and the inflammatory nature of exercise has been shown to elicit a similar response." (PMID 35565904, 2022). "Importantly, IL-6 levels were reported in severe patients and associated with persistent arthralgia, suggesting deleterious effects during infection." (PMID 35456119, 2022). "Besides, the levels of proinflammatory cytokines interleukin 6 (IL-6) and interleukin 1 beta (IL-1β) were higher during the resolution of infection, in peritoneal cavity or plasma of Alkbh5-deficient mice than WT littermates after a mild CLP." (PMID 35764614, 2022). "The down-regulatory effect of urolithin M5 on NF-κB, TNF-α and IL-6 was beneficial for the influenza virus-infected mice since excessive pro-inflammatory cytokines/chemokines may cause severe tissue damage after infection." (PMID 36080488, 2022). "In addition, it has been shown that using IL-6 inhibitors in autoimmune conditions increases the risk of severe infections and enhances the level of blood transaminase." (PMID 35619180, 2022). "Importantly, in the murine cytomegalovirus (MCMV) model of infection, Ifitm3 restricts infection-induced IL-6 mediated viral disease, lymphopenia and loss of NK and T cells without directly impacting CMV replication." (PMID 36075894, 2022). "Moreover, an increase in the concentration of CCL2, G-CSF, GM-CSF, and IL-6 was previously reported to be associated with local neutrophil recruitment upon infection." (PMID 35401577, 2022). "The higher level of IL-6 has been shown to play a role in infection-associated inflammation." (PMID 36431892, 2022). "However, when plasma samples from patients with infection were analyzed, the presence of the 67 kDa band was associated with the increased level of inflammatory cytokines, especially with IL-6." (PMID 36536294, 2022). "Moreover, even before infection, both total and B-cell-specific IL-6 deficiency resulted in a significantly diminished size of this important T-cell population in spleen (such an experiment is technically infeasible with non-infected lung tissue)." (PMID 35154093, 2022). "In this context, new emerging diagnostic and prognostic markers of infection could be useful in the prediction of the disease severity, as well as pro and anti-inflammatory cytokines involved in the cytokine storm, such as IL-6 and IL-10." (PMID 35740951, 2022). "A high level of circulating IL-6 could be associated with the severity of infection of the three coronavirus strains." (PMID 34046036, 2021). "Likewise, the levels of pro-inflammatory cytokines implicated in CA16 infection, namely, IL-1β, IL-6, IL-18, and IFN-γ, were found to be significantly elevated in infected hSCARB2 transgenic mice." (PMID 33882964, 2021).
infection (continued). "At early stages of infection, low levels of IL-6 may contribute to uncontrolled viral replication and cause acute lung pathology." (PMID 33670394, 2021). "Stimulation of the inflammatory response, either to an underlying disease or infection, results in abundant expression of cytokines, like tumor necrosis factor alpha (TNFα) and interleukin 6 (IL6), which lead to endothelial activation of adhesion molecules and further chemokine production." (PMID 34025658, 2021). "Furthermore, severe infections with SARS-CoV-2 are often associated with a cytokine storm resulting in high levels of IL-6 and TNF-α in the patients." (PMID 34122407, 2021). "In previous studies, IL-6 contributes to increasing susceptibility during infection." (PMID 33748220, 2021). "Previously, it is reported that GSK5182, an ERRγ inverse agonist, can inhibit IL-6-mediated hepcidin expression caused by infection of Salmonella typhimurium in hepatocytes, indicating that ERRγ can act as a transcriptional mediator in IL-6-mediated hepcidin induction." (PMID 34679725, 2021). "Notably, proinflammatory cytokine genes Il-1α, Il-6, Il-7, and Il-17, as well as anti-inflammatory genes Il-6 and Il-13, were downregulated after an infection caused by the 267/47 strain compared to those after infection with the H37Rv strain." (PMID 34442871, 2021). "Administration of LPS to wild-type mice increases Fgf23 gene and protein expression as early as the hepatic expression of the inflammatory cytokines Tnf, Il6, and Il-1b and causes hypoferremia as an acute phase response to infection and inflammation aiming to reduce iron availability for pathogens." (PMID 33416083, 2021). "Early upregulation of SAA and serum IL-6 may indicate the development of rejection or infection, and are associated with impaired kidney graft function." (PMID 34956220, 2021). "Finally, the IL-6 production was upregulated by HO-1 induction in T. gondii-infected cells, which was associated with the control of infection." (PMID 33912151, 2021). "The control of T. gondii proliferation and the improvement of the pathology due to infection, have been closely linked to IL-6 activity, since it was demonstrated the protective role of IL-6 against toxoplasmic encephalitis, using a model of knockout mice (IL-6–/–)." (PMID 33912151, 2021). "Because of its high sensitivity for infection IL-6 could be a useful addition in the diagnostic of low-grade PJI and should further be evaluated." (PMID 34040084, 2021). "IL-6 is also reported to increase prostaglandin productions from AECs and often referred in the literature as a “causal factor” for various adverse outcomes, specifically infection and inflammation associated PTB and pPROM." (PMID 32848846, 2020). "The CANTOS trial provided favorable evidence that inhibition of the IL-1β/IL-6 signaling cascade led to a significant reduction in cardiovascular risk, independent of a lipid-lowering effect, but with an increased risk of serious infection." (PMID 33614738, 2020). "TNF α, IL-6 and IL-12 increases in current depressive episodes underline the systemic nature of the inflammatory status, showing some similarity to the immune reaction to an active infection." (PMID 32113908, 2020). "Infection and other inflammatory challenges are associated with reactive hyperglycaemia, which may be aggravated in people with higher IL-6 levels." (PMID 33096487, 2020). "Infection with pH1N1-alone also resulted in upregulation in “Signaling by Interleukins”, with 44 associated proteins from our kinome arrays, in addition to upregulation of IL-1, IL-2, and IL-6." (PMID 33202895, 2020). "Furthermore, impaired IL-6 function causes enhanced susceptibility of mice to infection by various bacterial pathogens." (PMID 33322581, 2020). "IL-6 s in MP mixed infection group were significantly higher than those in MP single infection group, which suggested that IL-6 may be associated with other pathogens." (PMID 32393186, 2020).
infection (continued). "Interestingly, the upregulation of IL6 can play an important role in mucosal protection, associated with reducing infection-induced apoptosis in the epithelium and subsequent ulcerations." (PMID 33171908, 2020). "Furthermore, the risk of infection was assessed using objective indicators like IL-6, PCT, ESR, and CRP which eliminated observer bias." (PMID 32846864, 2020). "Up to now autoantibodies to four major groups of cytokines—IFN-γ, GM-CSF, to a group of TH-17 cytokines comprising IL-17A, IL-17F, IL-22, IL-23, and to IL-6—have been found to be causative or closely associated with increased susceptibility to selective infection." (PMID 32419033, 2020). "Treatment with 16,000 pg/mL IL-6, a concentration often seen in infection and inflammation associated pPROM, was used to determine if such a high dose IL-6 could induce AEC cellular pathologies compared to the term labor concentration (3,300 pg/ml)." (PMID 32848846, 2020). "We demonstrated that IL-6 is important for the control of B. abortus during the early phase of the infection, and demonstrated that the enhanced susceptibility in IL-6 KO mice occurs in conjunction with a decrease in type 1 cytokine secretion and reduced inflammatory cell recruitment." (PMID 33322581, 2020). "And, if the NIHSS score and interleukin-6 levels were higher, the risk of infection was greater." (PMID 32629702, 2020). "In addition, CCR5-deficiency during infection affected the upregulation of cytokine genes such as Csf2, Csf3, Cxcl1, Edn1, and Il6 and other genes associated with immune response (i.e., Gimap6, Mcoln2) and migration (i.e., Cyfip2)." (PMID 31506064, 2019). "Of note, enhanced IL-6 secretion in Unc93b1 mutated vs. Tlr13-deficient BMDMs was observed after infection with MOI 50, potentially by compensatory upregulation of TLR2 following its stimulation to counterbalance the loss of all endosomal TLRs under high bacterial load." (PMID 30846984, 2019). "Interestingly, IL-6 was significantly elevated following infection with neonatal infection-associated sequence type (ST)-17 strains and among strains possessing capsule (cps) type III." (PMID 31536604, 2019). "Moreover, IFN-γ cannot control infection alone and it requires the association of other molecules such as IL-6, IL-1 and the TNF-α." (PMID 31508399, 2019). "However, we found that the level of IL-33 in BAL fluids was much less than that of IL-6 and IL-12p40, and the survival of IL-33-deficient mice was similar to those of normal mice post-infection." (PMID 31509992, 2019). "As IL6 mediates a protective immune response against microbial infections, reduced IL6 expression observed in the placenta may predispose an individual to infection, by preventing an appropriate innate immune response to microbes." (PMID 30795743, 2019). "IL-6 was repeatedly associated with poor functional outcome, but whether this is an independent effect or a signal due to infection remains unclear." (PMID 30828313, 2019). "Interestingly, KSHV also encodes a viral homologue of IL6 (vIL6) with distinct signaling activity during lytic infection." (PMID 30486363, 2018). "Indeed, genes within the IL-17 pathway including Cebpb, Tnf, IL-6, Cxcl1, Cxcl2, Cxcl3, Cxcl5, Cxcl10, and Ccl7 were shown to be up-regulated in both susceptible and resistant mice during infection." (PMID 29339782, 2018). "An association between the levels of IL-6 and altered neurodevelopment of the salience network in human neonates gives a first glimpse of the mechanisms underlying how infection during pregnancy may prime the brain for mental disorders." (PMID 30344483, 2018). "We have carried out a longitudinal study to examine the association between exposures to infections during childhood between 1·5 and 7·5 years and subsequent serum concentrations of inflammatory markers (i.e. IL-6 and CRP) at age 9 years and general intelligence (i.e. IQ) at age 8 years." (PMID 29198208, 2018).
infection (continued). "Repeated infections during early childhood – a critical period of development for the immune system – would cause multiple spikes in serum IL-6 and CRP, which might programme the immune system for persistent low-grade immune activation." (PMID 29198208, 2018). "Moreover, induction of type 1 and 2 interferon (IFN) were higher following infection with African strains associated with enhanced levels of inflammatory cytokines such as interleukin 6 (IL6) or tumor necrosis factor (TNF)." (PMID 28934211, 2017). "Nevertheless, blockade of IL-6, which is a key pathway in immune defence, could raise the risk of serious infections in T1D patients and hence targeting the therapy to a specific cell type could offer advantages in therapy." (PMID 28284938, 2017). "Notably, IL-6−/− and WT lung fibroblasts were equally susceptible to infection by IAV, as assessed by detection of viral nucleoprotein (NP) and quantification of its expression." (PMID 28262742, 2017). "Targeting of IL-6 trans-signaling may also allow the beneficial anti-inflammatory actions of IL-6 cis-signaling to occur and reduce the infection hazard associated with the blockade of IL-6 cis-signaling." (PMID 28515477, 2017). "Chronic inflammation, whether it is related to “spillover” from airway inflammation inherent to COPD, genetically acquired polymorphisms, or recurrent infection, will cause the release of IL-6." (PMID 28403845, 2017). "In the present study, the histopathological symptoms and high expression of Il6, Il1, Ifng and Tnf demonstrated that the host was suffering from serious acute bacterial pneumonia, which could be caused by the infection and the detected cytokine cascade." (PMID 28899359, 2017). "In the early response to pathogenic infection, the monocytes of host immune system recognize pathogen-associated molecular patterns (PAMPs) via pattern recognition receptors (PRRs) and produce varied proinflammatory cytokines including IL-6." (PMID 28706517, 2017). "Blocking excessive IL-6 may be advantageous in limiting autoimmune phenomena in these patients; however, it must be balanced with the potential for neutralization of IL-6 to increase susceptibility to infection." (PMID 31557985, 2016). "Similarly, mortality was also increased in two other models of infection using either Escherichia coli or Streptococcus pyogenes infection in IL-6-deficient mice." (PMID 27057100, 2016). "However, our results showed no increase of TNFR2 expression in TNFR1-deficient mice, whereas WT and IL-6-deficient mice displayed an increase of TNFR2 after infection." (PMID 27057100, 2016). "In the i.n. model, infection by vΔ169 caused enhanced production of several cytokines (IL-2, IL-6 and TNF-α) and chemokines (CCL11, CXCL9 and CXCL10) within 1 day p.i. and subsequent greater recruitment of macrophages and CD4+ and CD8+ T cells and increased lung weight." (PMID 26334635, 2015). "Thus, even though IL-6 is important for the resolution of the infection, elevated levels of this cytokine are associated to exacerbated inflammatory responses, tissue damage and organ failure." (PMID 26126119, 2015). "In addition to IL-6, associations between infection/inflammation/PTB and a wide range of other amniotic fluid cytokines and chemokines have been described." (PMID 25273669, 2014). "In addition, WT GBS stimulated greater secretion of the pro-inflammatory cytokines TNF-α and IL-6 from Siglec-E deficient macrophages both at 6 h and 24 h post infection." (PMID 24391502, 2014). "In their paper, authors report these inflammatory markers' level and speculate that high preoperative levels of serum TNF-α and IL-6 may indicate a predisposition for postoperative inflammation and infection." (PMID 27438912, 2014).
infection (continued). "Infection of IL-6-deficient mice led to profound defects in lamina-propria-resident TH22 cell numbers, but not IL-22 production from other cells, relative to IL-23-deficient mice or WT counterparts, illustrating the importance of IL-6 in regulating TH22 differentiation." (PMID 24586147, 2014). "In addition to IL6, secretion of two other proteins encoded by IκBζ target genes, G-CSF and GM-CSF, was elevated after infection of HIBCPP cells." (PMID 25347003, 2014). "Elevated IL-6 levels are associated with disease severity triggered by pdmH1N1 infection in mice." (PMID 24465940, 2014). "These exciting results clearly indicate that the response of ‘arthritic’ osteoblasts to RRV infection differs from normal osteoblasts; they are more susceptible to infection possibly through delayed type I IFNs response and produce higher levels of IL-6, IL-1β, CCL2 and TNF-α." (PMID 25407789, 2014). "In addition, primary human osteoblasts were shown to be susceptible to CHIKV infection in vitro and infection induced IL-6 and RANKL secretion by these cells with similar kinetics, while osteoprotegerin secretion was gradually inhibited." (PMID 24069610, 2013). "In addition to histamine, calcium ionophore and phosphodiesterase inhibitors, ULVWF strings are secreted from endothelial cells that have been stimulated by cytokines (TNFα, IL-6, IL-8) associated with infection and inflammation." (PMID 23555663, 2013). "Interestingly, accumulation of copy-back DVGs during infection with SeV Cantell LD was associated with the expression of Ifnb and Il-6 mRNA in the lung." (PMID 24204261, 2013). "On the other hand, Th17 cells may protect susceptible mice at low levels of infection, but could, in association with IL-6, be pathogenic at high parasite loads." (PMID 23776551, 2013). "In addition, IL-6-deficient C57BL/6 mice were more susceptible to infection with the Tulahuén strain than wild type mice due to deficient lymphocyte recruitment." (PMID 23776551, 2013). "Moreover, an increase in the expression of IL-6 in susceptible mice was associated with lethality upon infection with a high parasite load." (PMID 23776551, 2013). "The remaining 2 cytokines (IL-17 and IL-6) showed only an association with infection." (PMID 23469125, 2013). "In mouse or ferret studies experimental infections with virulent strains of influenza A viruses have been associated with higher elevations in select biomarkers such as IL-6, TNF-α, and IFN-α and have usually been associated with worsened disease outcomes in those animals." (PMID 23468921, 2013). "Furthermore, in our lethal C57BL/6J mouse model of H1N1pdm infection, global gene expression analysis indicated a pronounced IL-6 associated inflammatory response." (PMID 22679491, 2012). "Furthermore, a statistically significant association between the level of IL-6 and the type of infection was present (P = 0.034)." (PMID 23724320, 2012). "We asked whether susceptibility to proliferation or IL6 expression was pre-determined by the differentiation state of B cells before infection." (PMID 21352549, 2011). "Postoperative infection was also associated with higher IL-6 levels." (PMID 19523233, 2009). "Infection of the porcine lung with A. pleuropneumoniae has previously been reported to result in a local production of proinflammatory proteins or mRNA encoding the cytokines interleukin (IL) -1α, IL-1β, IL-6 and the chemokine IL-8." (PMID 17466061, 2007). "Numerous studies have shown that IL-6 is able to function as an anti-inflammatory early marker that promotes the secretion of other inflammatory factors and amplifies the inflammatory response, and its expression level increases after the infection of pathogenic microorganisms." (PMID 40005807, 2025). "However, IL-6 inhibitors can increase a person’s risk of obtaining infections." (PMID 39857830, 2025).